SIRT7 (sirtuin 7)
Diseases named in the same sentence as SIRT7 in open-access papers (continued):
Sharing a sentence is not in itself a finding about the gene and the disease.
skin cancer (3 papers, 2019 to 2024). "Using transgenic tumor models, we show that SIRT7 insufficiency promotes the initiation, progression, and metastasis of breast and skin tumors." (PMID 34433808, 2021). "We show that SIRT7 suppresses breast/skin tumor development, thus indicating that targeting SIRT7 might have the dual benefits of anti-tumor activity and extended healthy lifespan." (PMID 34433808, 2021). "However, SIRT7 seems to manifest a safeguarding function against skin cancer initiation in mice." (PMID 38383727, 2024). "This is evidenced by the fact that SIRT7 heterozygous mice, subjected to the two-stage DMBA/TPA-induced skin cancer model, display a greater development of skin papillomas compared to their wild-type counterparts." (PMID 38383727, 2024).
type 2 diabetes (3 papers, 2022 to 2025). "Among a series of longevity-related pathways, SIRT1 and SIRT7 were downregulated in myeloid cells of individuals with type 2 diabetes and CCs, but only SIRT7 showed clear relationships with the extent of calcification and with MCC levels." (PMID 35708762, 2022). "A significant inverse correlation further supporting this link was observed between plasma miR-125b-5p levels and SIRT7 gene expression in MNCs of participants with type 2 diabetes (r=−0.46; p<0.001)." (PMID 35708762, 2022).
viral infection (3 papers, 2023 to 2025). "SIRT7 decreases IRF3/IRF7 phosphorylation to block the interaction between tbk1 and IRF3/IRF7, resulting in the suppression of antiviral responses, disruption of SIRT7 increases the survival rate of carp during virus infection." (PMID 40636259, 2025). "In addition to FBXO7, SIRT7 has also been reported to be polyubiquitinated by HIV-1 Vpr, a multifunctional accessory protein critical for efficient viral infection of target cells." (PMID 36646384, 2023). "KEGG pathway analysis identified enrichment in pathways related to viral infection, cancer, tight junctions, PI3K-Akt signaling, actin cytoskeleton regulation, cGMP-PKG signaling, Hippo signaling, and TNF signaling, suggesting that SIRT7 may regulate GPS infection via these signaling pathways." (PMID 40636259, 2025).
acute myeloid leukemia (2 papers, 2024). Acute myeloid leukemia (AML) is a group of neoplasms arising from precursor cells committed to the myeloid cell-line differentiation. "Of note, reduced SIRT7 expression is associated with hematopoietic disorders like acute myeloid leukemia (AML) and chronic myeloid leukemia (CML)." (PMID 37676263, 2024). "Recent investigations have shed light on a discernible decline in SIRT7 levels observed in acute myeloid leukemia (AML) and chronic myeloid leukemia (CML) when contrasted with levels in healthy donors." (PMID 38383727, 2024). "Finally, SIRT7 level may serve as a biomarker to monitor treatment response in acute myeloid leukemia (AML) or chronic myelogenous leukemia (CML) patients, as it is restored to normal level upon a positive treatment response but is reduced during disease relapse." (PMID 37676263, 2024).
angiosarcoma (2 papers, 2023 to 2024). A malignant tumor arising from the endothelial cells of the blood vessels. "Interestingly, angiosarcoma cells exhibit decreased SIRT7 expression, which correlates with suppressed cell proliferation and invasion." (PMID 38826780, 2024). "Additionally, miR-340 targeting SIRT7’s 3’-UTR to decrease angiosarcoma cell invasion and proliferation demonstrates the specificity of miRNA actions." (PMID 38826780, 2024). "Furthermore, SIRT7 can counteract the tumor suppressive effects of miR-340, highlighting its complex role in angiosarcoma." (PMID 38826780, 2024). "Similarly, miR-340 has been shown to inhibit the proliferation and infiltration of angiosarcoma cells by targeting SIRT7, further highlighting its potential as a tumor suppressor miRNA in this aggressive malignancy." (PMID 38826780, 2024). "Sirtuin 7 (SIRT7) was identified as a target gene of miR-340, with silencing of SIRT7 resulting in the inhibition of angiosarcoma cell proliferation and invasion." (PMID 36765536, 2023).
autoimmune disease (2 papers, 2021 to 2025). A disorder resulting from loss of function or tissue destruction of an organ or multiple organs, arising from humoral or cellular immune responses of the individual to their own tissue constituents. "According to previous reports, only SIRT1, SIRT6, and rarely SIRT7 in the sirtuin family have been associated with dermatologic issues, such as skin aging, skin inflammation, autoimmune disease, cutaneous infection/cancer, and inherited dermatologic disease." (PMID 34122721, 2021). "SIRT7 has been implicated in the pathogenesis and therapeutic modulation of autoimmune diseases." (PMID 40672112, 2025). "Recent studies have suggested a potential role for SIRT7 in autoimmune diseases." (PMID 40672112, 2025).
breast tumor (2 papers, 2021 to 2024). "The earliest evidence linking SIRT7 to cancer noted that SIRT7 level is higher in breast tumors than in normal breast tissue and is positively associated with a higher incidence of node-positive breast cancer." (PMID 37676263, 2024). "In contrast, SIRT7 overexpression significantly attenuates breast tumor development and lung metastasis." (PMID 34433808, 2021). "Sirt7 overexpression suppresses S-phase kinase-associated protein 2 (Skp2)-Culin1-F-box (SCF) E3 ligase-mediated AKT ubiquitination and TGF-β/SMAD family member 4 (SMAD4) signaling, thus antagonizing the growth of breast tumors and metastasis to distal organs." (PMID 37676263, 2024).
calcification (2 papers, 2022 to 2025). Process by which organic tissue becomes hardened by the physiologic deposit of calcium salts. "Notably, SIRT1, SIRT2, SIRT3, SIRT6, and SIRT7 have demonstrated therapeutic potential in the treatment of vascular calcification." (PMID 41480421, 2025). "Coronary calcification was associated with 2.8-times-higher myeloid calcifying cell levels (p=0.037) and 50% elevated expression of the osteogenic gene RUNX2 in mononuclear cells, whereas expression of Sirtuin-7 (SIRT7) was inversely correlated with calcification." (PMID 35708762, 2022).
cervical cancer (2 papers, 2019 to 2023). A primary or metastatic malignant neoplasm involving the cervix. "We hypothesized that SIRT7 may regulate the autophagy and oxidative stress in cervical cancer through USP39." (PMID 37957720, 2023). "Therefore, we assessed if USP39 acetylation was affected by SIRT7 in cervical cancer cells." (PMID 37957720, 2023). "However, the relationship between SIRT7 and USP39 in cervical cancer is not known." (PMID 37957720, 2023).
cervical squamous cell carcinoma (2 papers, 2023 to 2025). A squamous cell carcinoma arising from the cervical epithelium. "In this study, we aimed to elucidate the biological functions and the underlying mechanism of SIRT7 in cervical squamous cell carcinoma (CSCC) progression." (PMID 37957720, 2023). "Chi-square test results revealed that the expression of SIRT7 was positively correlated with the grade of cervical squamous cell carcinoma and nodal metastasis status." (PMID 37957720, 2023). "qRT-PCR and western blot analyses also validated the upregulation of SIRT7 protein levels in cervical squamous cell carcinoma cells (CaSki, SiHa, C-33A) compared with the normal Ect1/E6E7 cells." (PMID 37957720, 2023). "Also, we noticed that SIRT7 promoted autophagy while inhibited ROS accumulation in cervical squamous cell carcinoma cells." (PMID 37957720, 2023). "SIRT7 promoter region was found to be bind with FOXM1 in cervical squamous cell carcinoma cells." (PMID 37957720, 2023). "Finally, we wanted to explore whether SIRT7 regulates oxidative stress in cervical squamous cell carcinoma via USP39 and FOXM1." (PMID 37957720, 2023). "Whereas the function of SIRT7 in cervical squamous cell carcinomas is largely unknown." (PMID 37957720, 2023). "In cervical squamous cell carcinoma (CSCC), the deacetylation of USP39 by SIRT7 leads to the promotion of SIRT7 expression via FOXM1-mediate transcription, which subsequently enhances the development of CSCC." (PMID 40990019, 2025). "This positive feedback was then further verified using rescue assays, which indicated that indeed SIRT7 promoted the autophagy and inhibited ROS production through USP39 and FOXM1 in cervical squamous cell carcinoma." (PMID 37957720, 2023). "Moreover, SIRT7 expression was revealed to be downregulated after USP39 silencing, which was reversed after FOXM1 overexpression in cervical squamous cell carcinoma cells." (PMID 37957720, 2023). "SIRT7/USP39/FOXM1 is highly expressed in CSCC, but whether the pathogenesis in cervical squamous cell carcinoma patients is inhibited by acetylation of USP39 at the k428 site still needs further study." (PMID 37957720, 2023). "Sirtuin 7 (SIRT7) is an oncogene that promotes tumor progression in various malignancies, however, its role and regulatory mechanism in cervical squamous cell carcinoma (CSCC) is unknown." (PMID 37957720, 2023).
chronic myeloid leukemia (2 papers, 2024 to 2025). "Similarly, reduced SIRT7 expression—along with its association with less favorable clinical outcomes—has also been reported in hematologic malignancies such as acute and chronic myeloid leukemia (AML and CML, respectively) and B-cell acute lymphoblastic leukemia (B-ALL)." (PMID 41471367, 2025).
coronary artery disease (2 papers, 2022 to 2025). "The exact role of SIRT7 in hypertensive patients with coronary artery disease (CAD) remains elusive." (PMID 40884727, 2025).
endometrial cancer (2 papers, 2021 to 2024). Primary or metastatic malignant neoplasm involving the endometrium (mucous membrane that lines the endometrial cavity). "This clearly indicates SIRT7 participation in endometrial cancer formation and its susceptibility to treatment." (PMID 33435147, 2021). "Additionally, the authors observed that the knockdown of SIRT7 causes an increase in the sensitivity of endometrial cancer cells to cisplatin treatment in vitro." (PMID 33435147, 2021). "Similarly, the sensitivity of endometrial cancer cells to DDP treatment is enhanced after SIRT7 inhibition." (PMID 39020302, 2024). "SIRT7 was overexpressed in endometrial cancer cells when compared with normal endometrial cells, and, importantly, its downregulation inhibited the growth and invasiveness of endometrial cancer cells." (PMID 33435147, 2021).
Hypertension (2 papers, 2025). The presence of chronic increased pressure in the systemic arterial system. "Multivariate analysis confirms elevated SIRT7 as an independent risk factor for hypertension comorbid with CAD." (PMID 40884727, 2025). "Specifically, in a mouse model of hypertension, SIRT7 overexpression was associated with the activation of the KLF15/NRF2 axis." (PMID 39215785, 2025). "Targeting SIRT7 signaling may offer a new therapeutic strategy for hypertension-associated CAD." (PMID 40884727, 2025). "In summary, plasma SIRT7 levels are significantly elevated in hypertensive patients with CAD compared to those with isolated hypertension." (PMID 40884727, 2025). "Targeting the SIRT7 signaling pathway presents a promising new strategy for preventing and treating hypertension complicated by CAD, offering potential for more effective patient management and improved clinical outcomes." (PMID 40884727, 2025). "However, the interplay between SIRT7 and the coexistence of hypertension with CAD remains poorly understood." (PMID 40884727, 2025). "Obviously, in comparison to the hypertensive group, patients with hypertension and CAD exhibited a significantly higher level of SIRT7 (P < 0.001)." (PMID 40884727, 2025). "SIRT7 was recently indicated to reduce ferroptosis and fibrosis in renal epithelial cells and impair EMT and lipid peroxidation, thereby mitigating renal damage during hypertension." (PMID 39215785, 2025). "Thus, in patients suffering from hypertension concurrent with CAD, the body’s response to persistent inflammation might trigger a compensatory increase in SIRT7 expression." (PMID 40884727, 2025).
leukemia (2 papers, 2020 to 2024). A malignant (clonal) hematologic disorder, involving hematopoietic stem cells and characterized by the presence of primitive or atypical myeloid or lymphoid cells in the bone marrow and the blood. "Low SIRT7 levels were always associated with active disease (nonhealthy conditions), in both BCR-ABL- and FLT3-ITD-positive leukemias." (PMID 32214204, 2020). "Because SIRT7 activity strongly increased Pax5 levels in B cell progenitors, human B-ALL samples and cell lines, we propose that developing SIRT7-activating compounds to stimulate Pax5 functions may provide a basis for leukemia therapies." (PMID 39424985, 2024).
lymphoma (2 papers, 2019 to 2022). A malignant (clonal) proliferation of B- lymphocytes or T- lymphocytes which involves the lymph nodes, bone marrow and/or extranodal sites. "Only SIRT3 and SIRT7 were downregulated in lymphoma, AML and CML." (PMID 36230534, 2022).
mastitis (2 papers, 2019 to 2022). Inflammation of breast tissue during lactation or postpartum due to an obstructed duct or infection. "SIRT7 was significantly downregulated in the five tissue samples from mastitis cattle as compared to that in normal samples." (PMID 31285783, 2019). "The in vitro LPS-treated cell culture model showed a decrease in SIRT7, similar to that in cattle mastitis." (PMID 31285783, 2019). "We found that SIRT7 can attenuate LPS-induced upregulation of TLR4 and TAB1 and can also inhibit TAK1 phosphorylation, indicating that SIRT7 is involved in the TLR4-TAK1-TAB1-mediated NF-κB signaling pathway during cattle mastitis occurrence." (PMID 31285783, 2019). "Particularly, our results also demonstrated expression of SIRT7 decreased in pulpitis and was consistent with a recent report regarding mastitis, in which activation of NF‐κB was increased as well, but in which the relationship of SIRT7 and NF‐κB remained unclear." (PMID 35411569, 2022). "Considering the potent effects of SIRT7 and its function in inflammation, we hypothesized that SIRT7 might be involved in mastitis." (PMID 31285783, 2019). "Therefore, in the present study, we utilized a dairy cow mammary epithelial cell (DCMEC) model of LPS-induced mastitis to investigate the function of SIRT7 in the induction and progression of the inflammatory response." (PMID 31285783, 2019). "Therefore, SIRT7 may be considered as a potential pharmacological target for clinical mastitis therapy." (PMID 31285783, 2019). "However, whether SIRT7 is involved in the induction and progression of the inflammatory response, especially in cattle mastitis, remains unknown." (PMID 31285783, 2019).
mesenchymal
tumors (2 papers, 2015 to 2021). "Emerging evidence point toward SIRT7 as a therapeutic target for human cancer management because inactivate SIRT7 results in impairment of cancer transformation, increases chemosensitivity, and reverses metastatic phenotypes in both epithelial and mesenchymal tumors." (PMID 35174171, 2021).
pancreatic ductal adenocarcinoma (2 papers, 2015 to 2024). An infiltrating adenocarcinoma that arises from the epithelial cells of the pancreas. "The precise mechanisms through which DDX3X regulates SIRT7 expression in human pancreatic ductal adenocarcinoma (PDAC) cells have not been previously reported." (PMID 38316768, 2024).
pulpitis (2 papers, 2022 to 2023). Inflammation of the dental pulp. "In the pulpitis group, both p‐p65 and Ac‐p65 were expressed at higher levels, while SIRT7 showed a lower expression than in normal pulp." (PMID 35411569, 2022). "Combination of RvE1 and LXA4 effectively inhibited NF‐κB activation by upregulating SIRT7 expression in DPFs, leading to reduced production of pro‐inflammatory factors and promotion of pulpitis resolution." (PMID 35411569, 2022). "Additionally, the SPMs resolvin E1 and lipoxin A4 have been reported to inhibit NF-κB activation via sirtuins (Sirt1, Sirt6, and Sirt7) in pulpitis, supporting the therapeutic potential of a Sirt6 activator in periodontitis." (PMID 37445896, 2023). "We showed that combined administration of RvE1 and LXA4 could effectively promote pulpitis resolution by inhibiting NF‐κB activation via upregulation of SIRT7 expression, reducing expression of pro‐inflammatory factors." (PMID 35411569, 2022). "Combination of resolvin E1 and lipoxin A4 could effectively upregulate the expression of SIRT7, inhibiting nuclear factor kappa B activation by dephosphorylation and deacetylation in dental pulp fibroblasts, and promote pulpitis resolution." (PMID 35411569, 2022).
renal fibrosis (2 papers, 2025). A final common manifestation of a wide variety of chronic kidney diseases characterized by glomerulosclerosis and tubulointerstitial fibrosis. "A previous study indicates that SIRT7 reduces renal fibrosis by mitigating renal ferroptosis in hypertensive patients." (PMID 40448227, 2025).
rosacea (2 papers, 2023 to 2024). A chronic erythematous skin disorder that affects the face. "SIRT7 is upregulated in skin samples of patients and in mouse models with rosacea and can regulate gene transcription of TLR2 which activates NF-kB." (PMID 36993812, 2023).
tuberculosis (2 papers, 2023 to 2024). A chronic, recurrent infection caused by the bacterium Mycobacterium tuberculosis. "In a murine tuberculosis model, SIRT7 deficiencydetrimentally impacted host resistance to Mtb, whileSirt7 overexpression significantly increased the hostdefense against Mtb, as determined by bacterial burden andinflammatory–histopathological damage in the lung." (PMID 39287444, 2024). "We first analyzed the SIRT7 expression profiles of healthy controls (HC) andtuberculosis patients (TB)." (PMID 39287444, 2024).